S100P (S100 calcium binding protein P)
Diseases named in the same sentence as S100P in open-access papers (continued):
Sharing a sentence is not in itself a finding about the gene and the disease.
breast carcinoma (continued). "To verify our findings, we analyzed the TCGA breast cancer database and found that S100P gene expression levels in breast cancer tissue were higher than those in normal tissue (p < 0.001), which was consistent with our results." (PMID 33042844, 2020). "The adhesive ability of breast cancer cells decreased in both T47D by 84.32% and SK-BR-3 cells by 56.51% after the knockdown of S100P (p < 0.001, respectively)." (PMID 33042844, 2020). "The effect of S100P on the adhesion of breast cancer cells was assessed by Matrigel adhesion assay in vitro." (PMID 33042844, 2020). "The most transcriptionally upregulated gene in resistant tumours S100P, previously shown to be an inducer of breast cancer metastasis correlated with decreased survival." (PMID 30616553, 2019). "Our results indicated that high mRNA expression of S100A8, S100A9, S100A11 and S100P were found to be significantly correlated to worse outcome, while S100A1 and S100A6 were associated with better prognosis in all breast cancer patients." (PMID 28051137, 2017). "Previous studies of S100P in breast cancer have demonstrated that the expression of S100P correlates with breast cancer progression and decreased patient survival." (PMID 27449296, 2016). "Lastly, examination of RNA-seq of The Cancer Genome Atlas (TCGA) also demonstrated that S100P is highly upregulated in HER2+ breast cancer." (PMID 27449296, 2016). "It has also been reported that S100P expression in prostate and breast cancer cells is controlled by androgen and progestin, respectively." (PMID 25585623, 2015). "The expression of S100P has also been shown to be a potential prognostic biomarker in colorectal cancer, breast cancer, and diffuse large B cell lymphoma." (PMID 23785431, 2013). "Using a GEO gene expression database from 1,809 breast cancer patients, the Kaplan-Meier survival plots demonstrate the prognostic relevance of S100P overexpression on patient survival." (PMID 22417809, 2012). "In this respect, S100P gene or protein expression has already been proved to correlate with patient survival in lung and breast cancer, and it has been proposed as an early developmental marker of pancreatic carcinogenesis." (PMID 18282279, 2008). "In colon cancer cell lines, expression level of S100P correlated with resistance to chemotherapy, and in lung and breast cancer to decreased patient survival." (PMID 18282279, 2008). "In breast cancer cell lines, S100P overexpression seems to be an early event that has been suggested to play a role in the immortalization of human breast epithelial cells in vitro and tumor progression in vivo." (PMID 18282279, 2008). "However, S100P gene expression was higher in tumor tissue than in the normal one, which is important in order to consider this gene an important biomarker for breast cancer." (PMID 39594999, 2024). "Thus, S100P can be considered an excellent marker for breast cancer at the level of biopsy, blood, and/or plasma." (PMID 39594999, 2024). "However, our group and others have recently demonstrated the presence of a S100P in the plasma membrane of breast cancer cells and in epithelial cells of the suprabasal and upper layers of the human oesophageal epithelium by immunohistochemistry." (PMID 37627296, 2023). "Similarly, the migration of breast cancer cells with low levels of S100P decreased significantly both in T47D and SK-BR-3 cells (T47D by 19.72%, 48 h, p < 0.05; SK-BR-3 by 19.16%, 48 h, p < 0.01)." (PMID 33042844, 2020). "S100P promotes the aggressive properties of breast cancer cells and may be considered as a promising therapeutic target." (PMID 33042844, 2020). "Previously we have demonstrated that both S100A4 and S100P are able to promote metastasis in syngeneic rat models for breast cancer and that their overexpression in human primary breast cancers is associated with poor patient prognosis due to metastasis, at least to the brain and the liver." (PMID 32065231, 2020).
breast carcinoma (continued). "S100P has already been considered a treatment target for breast cancer." (PMID 32596149, 2020). "This phenomenon may be more related to the “HER-enriched” breast cancer subtype, suggesting that S100P may have a potential for the categorization of breast cancer and to be as a therapeutic target." (PMID 33042844, 2020). "Furthermore, we evaluated the effect of S100P on the chemosensitivity of breast cancer cells to cisplatin." (PMID 33042844, 2020). "From our present study, the expression levels of S100P in tumor tissue decrease dramatically after chemotherapy compared with pre-chemotherapy, indicating S100P may have a chemo-sensitive role in breast cancer." (PMID 33042844, 2020). "S100P is prominent among genes upregulated in primary breast cancer cells with high-grade tumors." (PMID 33042844, 2020). "Since S100P binding lowers IFN-β cytotoxicity to MCF-7 breast cancer cells, S100P inhibition could promote enhancement of anticancer activity of IFN-β." (PMID 33322098, 2020). "This suggests that S100P promoted cell proliferation by activating CCND1 protein in breast cancer." (PMID 33042844, 2020). "Moreover, S100P can be used to predict the therapeutic effect of chemotherapy in HER2+ breast cancer patients." (PMID 33042844, 2020). "However, in the HER2+ breast cancer cell line SK-BR-3, SK-BR-3 S100P KD cells are significantly resistant to paclitaxel and cisplatin compared with the vehicle control." (PMID 33042844, 2020). "Until now the role of S100P in the response of breast cancer to chemotherapeutic drugs remains unclear." (PMID 33042844, 2020). "ER+ breast cancer can escape antiestrogen treatment by up-regulating S100P." (PMID 33042844, 2020). "The expression levels of S100P in HER2+ breast cancer were higher than those in other subtypes." (PMID 33042844, 2020). "S100P, a small calcium-binding protein mediating Ca2+-dependent signalling pathways, has distinct functions in normal tissue and cancer, including human embryonic development and breast cancer initiation." (PMID 30616553, 2019). "Here, we also confirm the prognostic value of S100P high mRNA expression in breast cancer patients." (PMID 28051137, 2017). "Moreover, we accomplished knockdown experiments leading either to transient or stable S100P silencing in MCF-7 breast carcinoma cells that display endogenous S100P expression." (PMID 26967060, 2016). "Furthermore, truly prognostic patient group, that is, systematically untreated breast cancer patients with higher levels of S100P tend to have shorter relapse free period (P = 0.017)." (PMID 22417809, 2012). "The finding of overexpression of a metastasis-associated calcium- and zinc-binding protein encoding gene - S100A9 in CTCs suggests a valid targeting opportunity, demonstrated previously for another member of this family - S100P, in aggressive breast cancer cells." (PMID 22586443, 2012). "Besides pancreatic and breast cancer, S100P, originally isolated from a placenta, is overexpressed in tumors of the colorectum." (PMID 23166536, 2012). "Indeed, AGR2, LCP1 and S100P overexpression have been previously correlated with breast cancer progression, and we now link the aberrant expression of these genes with ErbB2 expression." (PMID 20840765, 2010). "S100P, which was down-regulated in the non-tumorigenic 12.2 cell line, is involved in cell growth and has been previously implicated in prostate and breast cancer progression." (PMID 16083501, 2005).
breast carcinoma (continued). "The implication of S100P in breast cancer chemotherapeutic drug response may be complicated." (PMID 33042844, 2020). "Additionally, S100P may be a biomarker to predict the therapeutic effects of chemotherapeutic agents in treating HER2+ breast cancer patients." (PMID 33042844, 2020). "S100P levels in patients with N3 lymph node metastasis was dramatically higher than that in N2 and normal tissues, and N2 > N1, N1 > N0 similarly (all p < 0.05), which suggested that S100P may be involved in breast cancer metastasis." (PMID 33042844, 2020). "S100P could be a promising therapeutic target in certain types of breast cancer." (PMID 33042844, 2020). "Therefore, our findings imply that S100P may have a role in predicting the drug sensitivity in HER2+ breast cancers." (PMID 33042844, 2020). "Moreover, S100P can also be used as a prognostic marker for breast cancer." (PMID 32819300, 2020). "Thus the conclusion that S100A9, S100A11 and S100P correlated to worse outcome in breast cancer patients seems plausible, and it’s required to further study the precise prognostic significance of them in breast cancer." (PMID 28051137, 2017). "Importantly, we found S100P to be upregulated in a cohort of breast cancer cell lines as compared to normal human mammary epithelial cells, demonstrating that S100P is upregulated from normal tissues to breast tumors, and further upregulated or stabilized in TzR tumors." (PMID 27449296, 2016). "Finally, S100P up-regulation appears to be significantly associated with reduced survival in ER(+) but not in ER(-) breast cancer patients." (PMID 22417809, 2012). "In further investigations, four breast cancer cell lines were screened for mRNA expression of MT1F, MT1E, SLC30A1, and S100P after treatment with BA or CAI3 and showed an upregulation of MT1F, MT1E, SLC30A1, and S100P in four breast cancer cell lines." (PMID 39594441, 2024). "S100P was also upregulated in DCIS patient blood samples, indicating its potential clinical utility as a non-invasive biomarker for breast cancer diagnosis by itself." (PMID 37445737, 2023). "This study shows that exposing HMECs to fluid flow upregulates genes identified clinically to be overexpressed during breast cancer development, including S100A7 and S100P." (PMID 35087607, 2022). "In breast cancer cell lines, it has been reported that the long non-coding RNA, NORAD, sequesters S100P, and its reduction in breast cancer cells allows S100P to exert its prometastatic roles." (PMID 34680103, 2021). "For example, lncRNA APOC1P1–3 has been found to inhibit breast cancer cell apoptosis by decreasing α-tubulin acetylation; lncRNA NORAD has been reported to suppress breast cancer metastasis by sequestering S100P." (PMID 32943090, 2020). "The interaction of S100P and IFN-β exhibits suppressed cytotoxicity toward MCF-7 breast cancer cells, implying that the antitumor activity of IFN-β is suppressed by S100P." (PMID 33042844, 2020). "Immunohistochemical analysis of S100P in 303 breast cancer samples revealed a sevenfold worse prognosis in patients with S100P positive expression compared to patients with negative expression of S100P." (PMID 40420099, 2025). "Finally, we evaluated expression of S100P and S100A7 in gene expression data from 517 patients presenting with the various molecular subtypes of breast cancer compared to expression in 104 healthy volunteers." (PMID 35087607, 2022). "For all different subtypes of breast cancer, high expression levels of S100P were all related to poor prognosis (data was not shown)." (PMID 33042844, 2020). "Our study demonstrates that S100P enhances cell proliferation by activating CCND1, and promotes cell migration and invasion through downregulating E-cadherin and upregulating Vimentin in breast cancer in vitro." (PMID 33042844, 2020). "This demonstrates that S100P does not play a significant role in chemotherapeutic drug response in HER2− breast cancer." (PMID 33042844, 2020).
breast carcinoma (continued). "The survival of breast cancer patients with S100P-positive cancers is significantly worse than those negative for S100P." (PMID 33042844, 2020). "It remains unknown whether S100P is also involved in resistance to hormone therapies and targeted therapies in HR+ HER2+ breast cancers, which may be the direction of further investigation." (PMID 33042844, 2020). "PR antagonism of 1 and analogues was assessed in T-47D breast cancer cells by measuring their effect in the presence of ORG2058, a highly active synthetic PR agonist that induces well-documented transcriptional targets including the FKBP54 and S100P genes." (PMID 30796232, 2019). "In addition, several proteins were identified by KM plotter as potential drug targets, such as S100P, carbonic anhydrase IX (CAIX), Notch1 in breast cancer, aldehyde dehydrogenase 1 (ALDH1) in NSCLC, Notch2 in ovarian cancer." (PMID 28061457, 2017). "The presence of extracellular S100P in promoting cell motility and invasion has not been reported in the context of trophoblast cells and has only recently been published in relation to breast cancer cell migration and invasion." (PMID 37627296, 2023). "However, this correlation is lost with ER(-) breast cancer patients (P = 0.95), suggesting that S100P is not a useful predictor in hormone independent breast cancer subtypes." (PMID 22417809, 2012). "However, the role of S100P in chemoresistance in breast cancer has not been thoroughly determined." (PMID 33042844, 2020). "However, the S100A10 expression level was not highly noticeable in the invasive breast cancers in our in silico analysis; rather S100A11, S100A14, and S100P were markedly elevated in the cancer tissues compared to those in normal breast tissues." (PMID 38595825, 2024).
lung carcinoma (25 papers, 2010 to 2025). "As an inflammation-associated biomarker, S100P holds particular promise for both CD diagnosis and potential cancer risk stratification, especially in liver and lung cancers." (PMID 40224483, 2025). "Notably, S100P displayed significant associations with immune cell infiltration and patient survival outcomes in both liver and lung cancers." (PMID 40224483, 2025). "S100P plays a stage-dependent and context-dependent role in lung cancer as observed from two different studies." (PMID 41164170, 2025). "We further determined S100P expression using a tissue microarray consisting of 30 primary lung cancer tissues and matched metastatic tissues." (PMID 38342601, 2024). "Intriguingly, we found that NTP treatment reduced the levels of RBMS1 and S100P in both A549 and H460 lung cancer cells in a dose‐dependent manner." (PMID 38342601, 2024). "Collectively, our clinical data reveal that RBMS1 is positively correlated with S100P in lung cancer patient samples." (PMID 38342601, 2024). "The levels of S100P mRNA and protein expression are higher in lung cancer, and upregulated S100P increases cancer cell migration and metastasis." (PMID 36052170, 2022). "During our analysis, increased expressions of PCDH7, DEPDC1B, SATB2, and S100P were detected in lung cancer tissues and adjacent normal tissue of TCGA-LUAD patients, but expression of FGD3 was observed to be lower." (PMID 36530971, 2022). "For lung cancer, S100P has been identified as a critical secreted factor in the modulation of cell migration and metastasis formation." (PMID 35597866, 2022). "The protein expression of HGF, PTX3, and S100P in lung cancer tissues and normal lung tissues was validated using the HPA online database." (PMID 34745947, 2021). "Increased S100P expression occurred in the tumor region in a cohort of 24 lung cancer cDNA array library, compared to matching normal regions." (PMID 26320193, 2015). "Further study has indicated that S100P knockdown prevents the spread of highly metastatic human lung cancer in animal models." (PMID 26320193, 2015). "This study demonstrates that S100P is highly expressed in the tumor region of lung cancer tissues and in the highly invasive lung cancer cell CL1-5, but is weakly expressed in normal regions of lung tissue and the less invasive CL1-0 cell line." (PMID 26320193, 2015). "In this study, we show that S100P increases cancer migration, invasion and metastasis in lung cancer cells." (PMID 26320193, 2015). "Conversely, knockdown of S100P suppressed migration and invasion, and caused a reversion of EMT in highly invasive lung cancer cells." (PMID 26320193, 2015). "Results from cell-based studies, mouse models, and clinical patient specimens suggest that S100P is a critical mediator contributing to the development of lung cancer." (PMID 26320193, 2015). "There were significantly increased S100P protein levels in the tumor region of lung cancer specimens, compared to normal regions in the patients (n = 5), as determined by immunofluorescence staining." (PMID 26320193, 2015). "Detection and targeted treatment of S100P-expressing cancer is an attractive therapeutic strategy in treating lung cancer." (PMID 26320193, 2015). "In conclusion, S100P interacts with integrin α7 to regulate lung cancer cell migration and invasion via the FAK/AKT-ZEB1 signaling pathway." (PMID 26320193, 2015). "More importantly, the tumor regions of specimens from lung cancer patients express higher amounts of S100P when compared to matching normal regions." (PMID 26320193, 2015). "Evaluated S100P mRNA transcript levels were also found in highly invasive lung cancer CL1-5 cells, when compared to isogenic less invasive CL1-0 cells." (PMID 26320193, 2015). "Additionally, S100P demonstrated potential as a prognostic and therapeutic biomarker in liver and lung cancers, further expanding its clinical relevance." (PMID 40224483, 2025).